IL6 (interleukin 6)
Diseases named in the same sentence as IL6 in open-access papers (continued):
Sharing a sentence is not in itself a finding about the gene and the disease.
Stroke (continued). "Our data show that pericytes in the ischemic stroke area upregulate Il6 compared to the other cell types at both 12 and 24 h after stroke." (PMID 37378751, 2024). "Elevated levels of IL-1β, IL-6, and TNF-α are closely associated with stroke occurrence, while some lipid-lowering drugs, such as statins, have been shown to reduce stroke risk through their anti-inflammatory effects." (PMID 38659020, 2024). "The present results show that HGS stroke patients have significantly higher circulating levels of IL-1β, whereas IL-6 levels only showed a trend to increase and TNF-α levels were unchanged." (PMID 36536168, 2024). "Inflammatory mediators produced by microglia, such as pro-inflammatory cytokines (TNF-α, IL-1β, and IL-6), significantly promote neuroinflammation, thereby mediating stroke." (PMID 38468280, 2024). "Some studies suggest potential benefits of IL-6 inhibition in improving stroke prognosis in RA patients, but more research is needed." (PMID 38294723, 2024). "we found that dysphagia, increased NIHSS scores, and increased IL-6 and HNL levelswere independent risk factors for stroke associated pneumonia." (PMID 38233767, 2024). "Several observational studies have reported associations of inflammatory biomarkers such as CRP, TNF-α, and Interleukin-6 (IL-6) with PSD/depressive symptoms after stroke." (PMID 37848651, 2024). "Circulating inflammatory and hemostatic biomarkers such as high sensitivity C-reactive protein (CRP), interleukin-6 (IL-6) and fibrinogen are the “usual suspects” and have been consistently associated with risk of CVD and stroke." (PMID 39145154, 2024). "Elevated levels of cytokines, including IL-1β, TNF-α, and IL-6, in the bloodstream of stroke patients imply a higher likelihood of deterioration of their condition." (PMID 38742047, 2024). "For example, in conditions like multiple sclerosis or stroke, the peripheral levels of cytokines such as interleukin-6 (IL-6), tumor necrosis factor-alpha (TNF-α), and interleukin-1 beta (IL-1β) have been found to be elevated." (PMID 38285083, 2024). "H. pylori also increases the production of inflammatory mediators such as IL-6 and TNF-α, contributing to systemic inflammation and the risk of stroke." (PMID 39202269, 2024). "Lower concentrations of IL-4, IL-6, and TNF-α were negatively correlated with stroke patients suffering from hyperhomocysteinemia (IL-4: P = 0.015, χ2 = 6.040; IL-6: P = 0.015, χ2 = 6.038; TNF-α: P = 0.016, χ2 = 6.243)." (PMID 38287458, 2024). "In an observational study of over 10,000 stroke patients, higher serum IL-6 demonstrated a significant correlation with the incidence of recurrent stroke and functional impairment." (PMID 39063013, 2024). "Thus, stroke recovery in patients with only the relevant IL-6 polymorphism (rs1800795) may have additional risk insofar as differential IL-6 levels could functionally mimic CRP rs1130864 which increases CRP levels in Han Chinese populations and leads to worse outcomes." (PMID 38502340, 2024). "A study of 188 AIS patients and 90 stroke mimics reported on a biomarker panel including IL-6, S100B, and MMP-9 which was incorporated in a clinical data assessment (age, AF, Face-Arm-Speech-Test results)." (PMID 39091977, 2024). "In stroke patients, markers like interleukin-6 (IL-6), tumor necrosis factor (TNF), and neutrophil counts were markedly increased." (PMID 38699426, 2024). "Therefore, future investigations are crucial in identifying whether neuroinflammatory agents, such as TNF-a, IL-6, or IL-1b, contribute to the association of stroke risk with RA and whether these agents are similarly influential in other inflammatory diseases, such as ankylosing spondylitis." (PMID 38294723, 2024). "Brain ischemic injury caused by stroke leads to systemic inflammatory responses and the production of various inflammatory mediators such as TNF‐α, IL‐6, and IL‐1β, which are also involved in the neuroinflammatory mechanisms of PSD." (PMID 38376033, 2024).
Stroke (continued). "In patients with AFIB, baseline IL-6 and TNFα levels were found to be significant predictors for ischemic stroke, and IL-6 levels were higher in AFIB patients at high risk of stroke." (PMID 38256155, 2024). "The only previous report of cytokine measurement in CSF from dogs with naturally occurring stroke assessed for IL-2, IL-6, IL-8, and TNF." (PMID 37266378, 2023). "Higher waist-to-hip ratio (WHR) and BMI result in an elevated deep-to-periventricular white matter hyperintensities ratio through elevated interleukin-6, which can increase the likelihood of stroke occurrence." (PMID 37337187, 2023). "IL‐13 and IL‐4 have been shown to increase IL‐6 production, and elevations in both IL‐13 and IL‐4 demonstrate reparative effects following stroke in mice models." (PMID 36478506, 2023). "Another possibility is to trigger a transcription factor, such as STAT3 activity by cytokine, e.g., IL6 delivery in the acute phase of a stroke to trigger a pericyte response prior to endogenous IL6 release and response." (PMID 36982744, 2023). "Interleukin-6 (IL-6) concentrations have been shown to correlate with stroke severity, functional outcomes within 1 year, and infarct size." (PMID 36673655, 2023). "The proangiogenic effect of IL-6 is closely associated with the early activation of angiogenesis-related gene transcription and STAT3 phosphorylation in the delayed phases after stroke." (PMID 36873773, 2023). "Inhibit stroke-induced inflammatory response by decreasing the number of Ly-6Chigh MMs subset and reducing expression of TNFα, IL-6, IL-1β and MCP-1." (PMID 37342335, 2023). "For example, TNF-α was elevated two- to three-fold in severe and mild-to-moderate stroke, whereas IL-6 had a nearly 30-fold increase in severe stroke and only a 10-fold increase in mild-to-moderate stroke." (PMID 37446092, 2023). "Based on information from the manufacturer, the limit of detection for IL-6 in the previous study was 2.4 pg/ml, and the median concentration of IL-6 in dogs with stroke was 6.6 pg/ml." (PMID 37266378, 2023). "The expression of pro-inflammatory factors such as tumor necrosis factor (TNF), interleukin-1 (IL-1) and interleukin-6 (IL-6) is increased in the infarct region, and both infiltrating and resident cells jointly regulate the inflammatory response after stroke." (PMID 38203348, 2023). "We found significantly increased levels of plasma IL-6 at 3 days (P < 0.01) after stroke in aged mice compared to age-matched shams." (PMID 37805585, 2023). "Again, to date, no clinical trials have addressed directly the potential benefit of IL-6 inhibitors for stroke prevention." (PMID 37762627, 2023). "Elevated levels of inflammatory biomarkers, such as C-reactive protein (CRP), interleukin-6 (IL-6), and tumor necrosis factor-alpha (TNF-α), have been associated with poor stroke outcomes, including increased mortality, disability, and recurrent stroke risk." (PMID 37468969, 2023). "This study also found that IGF-1 treatment inhibited levels of inflammatory cytokines such as TNF-α, IL-1β, and IL-6 at 4 h after stroke, while only IL-6 and IL-13 continued to be inhibited at 24 h after stroke, as did chemokines GRO-KC and CCL2." (PMID 37638322, 2023). "The AtheroExpress investigators reported that plaque harvested within 30 days of stroke or TIA expressed high levels of pro-inflammatory cytokines IL-6, IL-8, MMP-8, MMP-9 and dense macrophage infiltration." (PMID 41541100, 2023). "Elevations in IL‐6 at least 3 weeks after initial lacunar stroke predict recurrent vascular events, such as stroke, vascular death, and myocardial infarction." (PMID 36478506, 2023). "Previously, it was shown that immune (e.g., CRP, IL-6) and metabolic biomarkers (e.g., BMI and FBG) increase stroke risk and contribute to a worse outcome (see reviews:)." (PMID 36671047, 2023).
Stroke (continued). "Blood-based biomarkers for differentiating stroke subtypes include but are not limited to interleukin-6 (IL-6), D-dimer, C-reactive protein (CRP), and B-type natriuretic peptide (BNP)." (PMID 36644582, 2023). "Regarding inflammatory processes following stroke, IL‐6 plays a significant role in IS and HS pathophysiological processes." (PMID 36478506, 2023). "Administration of partial MHC class II construct, DRmQ, to rat models of IS, reduces splenic contributions to neuroinflammation, including amplifying splenic IL‐6 production, and decreases stroke pathogenesis." (PMID 36478506, 2023). "Some animal stroke experiments have reported that lymphocytosis upregulates IL-10 levels and inhibits inflammatory cytokines such as IL-6 and TNF-α, thus exerting neuroprotective effects." (PMID 37616313, 2023). "Three major pro-inflammatory cytokines—IL-1β, TNF-α, and IL-6—both mediate and aggravate the inflammatory response following stroke." (PMID 38102677, 2023). "On the other hand, IL-1β and IL-6 were increased in the blood and brain in stroke mice that received valeric acid or transplantation of old mouse feces." (PMID 37697393, 2023). "IL-6 expression is increased after ACI and can be used as a predictor of stroke-associated infection." (PMID 37119591, 2023). "With intraperitoneal administration of EA 24 h pre-stroke, EA reduced the serum protein expressions of proinflammatory cytokines iNOS, IL-1, IL-6, and TNF-α in the cerebral global ischaemic stroke animal model." (PMID 36675019, 2023). "Of them, genetically-predicted plasma soluble IL6 receptor (sIL6R), an IL6 signaling biomarker, showed robust evidence for an inverse association with CAD and stroke supporting a key role of inflammation in CVD which has also supportive RCT evidence." (PMID 37804188, 2023). "Increased IL-6 values were significantly associated with a higher risk of MACE (composite of CV death, MI or stroke), CV death, MI, HF, and all-cause mortality." (PMID 36676179, 2023). "In the early stages following stroke, IL‐6 is vital in inducing an inflammatory cascade and eventually inducing the activity anti‐inflammatory mediators." (PMID 36478506, 2023). "IL‐6 is also important for hematopoietic stem cell differentiation, and stem cells have been proposed as a revolutionary treatment for stroke." (PMID 36478506, 2023). "The authors identified a cutoff point (2.0 pg/mL) as a threshold for selecting patients who would benefit from anti-IL-6 drugs for stroke prevention." (PMID 37762627, 2023). "IL‐6 is a well‐characterized proinflammatory cytokine that provokes and aggravates an inflammatory response after stroke." (PMID 37287421, 2023). "The secondary outcomes included troponin I (cTnI) and creatine kinase-MB (CK-MB), inflammatory biomarkers (procalcitonin and interleukin-6, etc.), and adverse events (30-day mortality, stroke, ECMO and IABP use, etc.)." (PMID 36747296, 2023). "Production of other pro-inflammatory cytokines (TNF-alpha, IL-6) is significantly increased at 24 h of stroke which also initiates the synthesis of anti-inflammatory cytokines to protect the tissue itself (TGF-beta, IL-10)." (PMID 37822799, 2023). "The authors identified a cutoff point (2 pg/mL) as a threshold for selecting patients who would benefit from anti-IL-6 drugs for stroke prevention." (PMID 37762627, 2023). "Clinically, circulating IL-6 is increased after stroke, especially in patients with infarct sizes greater than 3 cm." (PMID 36745280, 2023). "IL-6 released after a stroke can worsen cerebral vascular damage by activating NMDI-Rs and upregulating ET-1 and JNK." (PMID 36793730, 2023). "This category includes Interleukin-6 (IL-6) and YKL-40, which were demonstrated in a separate study to be linked with stroke recurrence." (PMID 37606397, 2023). "Mediation analyses revealed that 18.72% (95% CI, 9.26%–28.18%) of the relationship between IL‐6 and functional disability was mediated by stroke recurrence." (PMID 37287421, 2023).
Stroke (continued). "Valeric acid increased the concentrations of IL-17, IL-1β, and IL-6 in the blood of mice with experimental stroke." (PMID 37697393, 2023). "Interleukin‐6 (IL‐6) is a critical post‐stroke proinflammatory cytokine and a marker of inflammatory burden." (PMID 37287421, 2023). "We aimed to use post‐stroke proinflammatory cytokine interleukin‐6 (IL‐6) as a marker of inflammatory burden and quantify post‐stroke inflammation's direct and indirect effect on functional disability." (PMID 37287421, 2023). "Specific inflammatory blood markers correlate with outcomes after stroke, including proinflammatory cytokines like IL-1, IL-6, TNF, as well as anti-inflammatory cytokines like TGF and IL-10." (PMID 36691064, 2023). "TNF and IL-6 are potent, proinflammatory cytokines that significantly increase within the initial 24 hours following a stroke." (PMID 38313176, 2023). "Interleukin-6 (IL-6) is an important inflammatory cytokine that is involved in the pathogenesis of various neurological disorders including strokes by acting as a messenger molecule between vascular endothelium, leukocytes, and parenchymal cells." (PMID 37342100, 2023). "The level of glutamate and IL-6 were elevated in patients with stroke onset between midnight and 8:00 h." (PMID 36835156, 2023). "On the contrary, IL-6 has a protective effect in ischemic stroke that helps improve post-stroke angiogenesis." (PMID 37754054, 2023). "Clinical studies have shown that plasma IL-6 levels increase in patients with TIA or AIS, and plasma IL-6 concentration can predict the severity and clinical prognosis of stroke." (PMID 37854582, 2023). "Clinical study in patients showed that IL-6 protein levels in cerebrospinal fluid were significantly increased on days 2 and 3 after stroke and then returned to normal levels 1 week later." (PMID 36819786, 2023). "When the highest quarter of IL-6 levels was compared with the lowest quarter, raised IL-6 was strongly associated with both MACE and recurrent stroke (MACE RR 1.35, 95% CI 1.09–1.67; recurrent stroke RR 1.33, 95% CI 1.08–1.65)." (PMID 41541100, 2023). "The mRNA expression of proinflammatory cytokines, including TNF-α and IL-6, was significantly elevated at 5 d after stroke in Sig-1R-/- mice." (PMID 36632219, 2023). "Genetic contributions to IL‐6 levels are significant in predicting stroke occurrence and prognoses, with lower genetically induced production of IL‐6 being protective against IS." (PMID 36478506, 2023). "Given the role of IL‐6 in inflammation following stroke, it is understandable that blocking this cytokine prior to potential exacerbated inflammation offers therapeutic benefit." (PMID 36478506, 2023). "IL‐6 is a cytokine engaged in the proinflammatory process after stroke, which is mediated by the Janus kinase 2 (JAK2) and the signal transducer and activator of transcription 3 (STAT3) pathway." (PMID 37143406, 2023). "In our study, we found elevated levels of plasma IL-6 and keratinocytes-derived chemokine (KC) in aged animals 3 days after stroke compared to sham animals, and cromolyn attenuated the stroke-induced elevation in HA, IL-6 and KC." (PMID 37805585, 2023). "During the early stages of stroke, IL-1 mediates harmful inflammatory processes, such as the upregulation of IL-6, TNF-α, Matrix metallopeptidase 9 (MMP-9), and chemokines in astrocytes, inhibition of neurogenesis." (PMID 36793730, 2023). "Triglyceride and leptin levels as well as IFN-β, IFN-γ and TNF-α were elevated with higher BMI values, and the IL-6 concentration was reduced with higher BMI values after stroke in our data." (PMID 37587512, 2023). "In concordance with other human and animal reports, that study reported elevations of IL-6 in CSF and plasma from dogs with stroke." (PMID 37266378, 2023). "IL-6 was found to be elevated in severe strokes (defined as NIHSS scores 21–42) and a residual of chronic (>1 week) changes after strokes." (PMID 37446092, 2023).
Stroke (continued). "The interleukin-6 (Il6 or IL-6) is one of the interleukins and a major cytokine, produced by microglia under stroke." (PMID 37229192, 2023). "Further research is needed, however, to enhance understanding of the B/T ratio following stroke and examine how IL‐6 signaling interventions should be administered in relation to this ratio." (PMID 36478506, 2023). "The biomarkers CLEC4G, CKAP4, IL6, LY75 and ITGA11 were found to be significantly associated with stroke severity as measured by mRS and in case of IL6 and ITGA11 also by NIHSS." (PMID 37468969, 2023). "As an example, IL-6 is a key biomarker for SAP in the first 2 years after stroke (OR: 19.2; 95%CI: 3.68, 100; p < 0.001)." (PMID 37065465, 2023). "IL-6 is marginally expressed in normal brain tissue, but significantly elevated in response to injury and stroke." (PMID 36145501, 2022). "Another study described that the increased production of IL-6 begins as early as 4–6 h after a stroke and peaks after about 12 h, before dropping off again." (PMID 36430226, 2022). "Numerous studies indicate that stroke lesion size positively correlates with measured IL-6 and TNF-α levels." (PMID 36567842, 2022). "In human studies, the serum level of IL-6 is significantly correlated with infarct size and survival in stroke." (PMID 36127663, 2022). "Although only a few studies have reported on the relationship between breathing exercises and IL-6 in patients with stroke, several studies have been conducted on different sets of participants." (PMID 35629013, 2022). "The level of interleukin-6 (IL-6), a pro-inflammatory cytokine, is elevated in plasma and brain 3–24 h after experimental stroke." (PMID 35493318, 2022). "Interleukin-6 (IL-6) was shown to be a stronger predictor of incident coronary disease, stroke, and cardiovascular mortality than C-reactive protein (CRP)." (PMID 36555671, 2022). "Additional support for reduced levels of TNF-α, and IL-6, in addition to IL-1β, comes from studies of chronic metformin pre-treatment in a rodent model of adult stroke." (PMID 35705953, 2022). "Yet, few retrospective clinical studies have provided evidence that pro‐inflammatory mediators such as IL‐6 and IL‐1β remained elevated in circulation even 3 months after stroke onset." (PMID 35971650, 2022). "Elevation of interleukin-6 (IL-6), an inflammatory marker of stroke, has been reported to be a poor prognostic factor." (PMID 36157893, 2022). "IL-6 is a marker of inflammation after stroke, and elevated IL-6 is mainly secreted from neurons, microglia, astrocytes, and endothelia cells in the ischemic hemisphere, traditionally regarding as an adverse prognostic factor." (PMID 35173738, 2022). "It has also been shown that higher levels of IL-6 in the acute phase of stroke and on the first and seventh days, and TNF-α during onset, were associated with poorer early and late prognosis in patients treated with intravenous thrombolysis." (PMID 36142524, 2022). "The peripheral inflammatory response following stroke is also heavily reliant on IL-6 signaling, as shown in studies examining spleen involvement." (PMID 36555094, 2022). "Further subgroup analysis of the drugs targeting the central IL-6 inflammatory signaling pathways showed that colchicine can reduce the incidence of isc hemic stroke to more extent." (PMID 35246052, 2022). "A propensity matched sample from > 3000 Salford Kidney Study (SKS) patients, differentiated by previous stroke at study recruitment, had stored plasma analyzed for interleukin- 6 (IL-6), Von Willebrand Factor (VWF) and C-reactive protein (CRP)." (PMID 35042473, 2022). "Stroke induces an acute inflammatory response characterized by elevated levels of a series of cytokines such as IL-1β, IL-6, and TNF-α in the cerebrospinal fluid." (PMID 35467483, 2022). "Further research is needed to best understand which IL-6 signaling pathway is employed at different time points following stroke to induce recovery." (PMID 36555094, 2022).